ERBB2 (erb-b2 receptor tyrosine kinase 2)
Diseases named in the same sentence as ERBB2 in open-access papers (continued):
Sharing a sentence is not in itself a finding about the gene and the disease.
breast cancer (continued). "In transgenic mouse models of mammary carcinoma, driven by Erbb2 and polyomavirus middle T-ag (PyMT), germline Akt1 gene ablation inhibited primary tumor development and, although increased tumor invasiveness, it did not increase the risk of metastasis." (PMID 39614261, 2024). "Migration and invasion enhancer I (MIEN1) and growth factor receptor-bound protein 7 (GRB7) are genes located proximal to the ERBB2 gene and are concomitantly overexpressed in HER2-positive breast cancer subgroups." (PMID 39482530, 2024). "In experiments on mice conducted in vivo, acetylation-deficient mutants of PPARγ1 showed reduced lipid synthesis in ErbB2-overexpressing breast carcinoma cells." (PMID 37935080, 2024). "The results suggested that the conserved lysine residues K154/K155 of PPARγ1 are acetylated and play an important role in lipid synthesis in ErbB2-positive breast cancer cells." (PMID 37935080, 2024). "Among the amplification driver genes, NRAS (in breast carcinoma and skin melanoma), ERBB2 (in gastric carcinoma, esophageal carcinoma), and NFATC2 (in ovarian carcinoma and pancreatic carcinoma) were identified in more than one cancer type." (PMID 38195844, 2024). "Invasive lobular carcinomas most often represent a hormone receptor‐positive, ERBB2‐unamplified luminal intrinsic subtype that accounts for 10–15% of all breast carcinomas." (PMID 38335502, 2024). "Trastuzumab deruxtecan (T-Dxd), an antibody-drug conjugate (ADC) targeted at HER2, has recently gained approval in the USA and Europe for treating HER2-low breast cancer, which is currently defined as IHC scores of 1+ or 2+ without ERBB2 ISH amplification." (PMID 38337757, 2024). "HER2/ERBB2 evaluation is necessary for treatment decision-making in breast cancer (BC), however current methods have limitations and considerable variability exists." (PMID 38374091, 2024). "Human epidermal growth factor receptor 2-positive (HER2+) breast cancer (BC) is a clinically and biologically heterogeneous disease characterized by the amplification of the ERBB2/HER2 gene and/or overexpression of its related kinase receptor protein." (PMID 38587643, 2024). "ERRα’s expression correlated with high Her2/ErbB2, a tyrosine kinase receptor amplified in 15% to 25% of breast cancers that also confers aggressiveness and that increases ERRα’s transcriptional activity via phosphorylation through MEK/MAPK and PI3K/Akt." (PMID 37175690, 2023). "One such example is trastuzumab, which was approved by the US Food and Drug Administration in 2006 for the treatment of ERBB2 (formerly HER2 or HER2/neu) overexpression in breast cancer." (PMID 38138934, 2023). "The expression of HK2, which can be induced by erbB2/Neu, was significantly increased in breast cancer specimens compared to normal tissue." (PMID 37377974, 2023). "In the TROIKA trial, patients with ERBB2-positive early breast cancer were randomized and treated with either HD201 or the referent trastuzumab." (PMID 36721174, 2023). "Interrogation of ERBB2 amplification in breast cancer has led to therapeutic success, but trials of drugs targeting HER2, including trastuzumab, pertuzumab and lapatinib, have yielded poor results in ovarian cancer." (PMID 36804485, 2023). "Exosomal AFAP1-AS1 confers the trastuzumab-resistant phenotype in breast cancer cells by inducing the translation of the ERBB2 protein." (PMID 36765853, 2023). "It has been reported that cell aggregation inhibits anoikis after ECM-detachment in Her2 (ErbB2)-positive breast cancers." (PMID 37866630, 2023). "Trastuzumab, a humanized anti-ERBB2 (epidermal growth factor receptor 2) monoclonal antibody (mAb), is commonly used to treat breast cancer in clinical settings by using alone or with other drugs, such as anthracycline and paclitaxel." (PMID 37297017, 2023). "Cells with ectopic NGFR-EGFR-FRB and NGFR-Erbb2-FKBP were selected subclonally for expression at levels comparable to endogenous EGFR and ERBB2 in breast cancer lines." (PMID 37055441, 2023).
breast cancer (continued). "ErbB2 (also referred to as HER2) is most widely known for its roles in breast cancer, in which the ErbB2 receptor is overexpressed in 25% of tumors." (PMID 37887421, 2023). "A study in 2009 reported that breast cancer cells positive for ERBB2 (an epidermal growth factor receptor, a marker of poor prognosis) produce large amounts of fat due to the activation of PPARγ, a key pathway for these cells to produce energy and survive." (PMID 37251321, 2023). "Lapatinib and neratinib are approved for the treatment of HER2-positive breast cancer, which targets ErbB2." (PMID 36768973, 2023). "The overexpression of ERBB2 disrupts normal cell-control mechanisms, gives rise to aggressive tumor cells, and leads to increased breast cancer metastasis." (PMID 36857450, 2023). "In another study, it was found that the YY1 transcription factor activates the activator protein 2-alpha (AP-2α) activity on the oncogenic promoter ERBB2, which is found in several breast cancer tumors." (PMID 37686541, 2023). "We also found that the expression of ERBB2 (or HER2), which is typically used to classify one of the major types of breast cancer, was found to be upregulated in LAR." (PMID 36672350, 2023). "In breast cancer, a high expression level of COX2 is tightly associated with ErbB2 expression, and it has been discovered that nuclear ErbB2 interacts with multiple genomic targets, including the promoter of COX2 gene." (PMID 36880347, 2023). "This newly discovered in vitro and in vivo mechanism of ErbB2-activated glycolysis in breast cancer cells has contributed significantly to the advancement of precision therapeutic approaches." (PMID 38202657, 2023). "In advanced-stage ERBB2-positive breast cancer patients, several vaccines targeting ERBB2 have shown promise, although early attempts targeting this protein resulted in only “short-lived peptide-specific immunity”." (PMID 36980723, 2023). "We generated xCTnull BALB/c mice to investigate the role of xCT in the immune system and xCTnull/Erbb2-transgenic BALB-neuT mice to study the role of xCT in a mammary cancer-prone model." (PMID 37770957, 2023). "The neoadjuvant setting can be definitively considered the new era for development in ERBB2-positive breast cancer." (PMID 36721174, 2023). "In an immunocompetent syngeneic mouse model of ErbB2-induced breast cancer, we next show that carbonic anhydrase inhibitors (c) acidify the tumor microenvironment, (d) lower immune infiltration and chronic tumor inflammation, and (e) accelerate tumor growth." (PMID 37098526, 2023). "By synthesizing high amounts of lipids, ERBB2-positive breast cancer cells generate palmitate-induced lipotoxicity." (PMID 37607964, 2023). "The reduction of ErbB2 levels following treatment with proteasome inhibitors has also recently been observed in breast cancer cell lines, where it has been ascribed to both transcriptional downregulation and the induction of lysosomal degradation mechanisms." (PMID 37069690, 2023). "It was previously shown that ligand‐dependent PlexinB2 activity elicits ErbB2 tyrosine phosphorylation and oncogenic signaling in breast cancer cells." (PMID 36722641, 2023). "The primary objective was to compare the pCR rate of the standard neoadjuvant treatment combination of docetaxel, trastuzumab, and pertuzumab (DTP) with T-DM1 monotherapy in ERBB2-positive breast cancer patients." (PMID 38352694, 2023). "The use of HER2/ERBB2-targeted vaccines has shown potential in the fight against breast cancer, with different HER2-based vaccines being developed over the years." (PMID 38140209, 2023). "The detection of 10 common DEPs across all three Tz-resistant cell lines offers promising avenues for future therapeutic interventions, providing potential targets to overcome Tz resistance and potentially improve patient outcomes in ERBB2+ breast cancer." (PMID 37367744, 2023).
breast cancer (continued). "Human epidermal growth factor receptor 2 (HER2, which is encoded by the ERBB2 gene), is amplified and/or over-expressed in 10%-25% of human breast cancers, being as it is a member of the epidermal growth factor receptor family." (PMID 36793527, 2023). "Previous studies have found that NRG1-ERBB3/ERBB2 axis triggers anchorage-independent growth of basal-like breast cancer cells." (PMID 37879219, 2023). "In the younger cohort, patients with ERBB2+ subtype PBC and family history of breast cancer had increased risk of developing CBC." (PMID 38100108, 2023). "circ-ERBB2 acts as a ceRNA for miR-136-5p or miR-198 to relieve the repressive influence of miR-136-5p or miR-198 on TFAP2C in breast cancer." (PMID 37291585, 2023). "Mammary cancer in felids is commonly described as a model for HER2-overexpressing-hormone independent human breast cancers, which is why information about the ERBB family in these species almost exclusively focuses on ERBB2." (PMID 37219601, 2023). "An ongoing clinical trial is currently evaluating the role of T-DXd as adjuvant therapy for early-stage ERBB2 low breast cancer." (PMID 38138928, 2023). "Subsequent work revealed that in ErbB2-amplified human breast cancer cells, ErbB2 activates HSF1, which in turn binds to the LDHA gene promoter to induce LDHA expression and promote glycolysis and growth." (PMID 37444501, 2023). "In this cohort study of 103 605 patients with early-stage breast cancer who received neoadjuvant chemotherapy, Black patients had more refractory disease in ERBB2-positive and triple-negative breast cancer." (PMID 37991763, 2023). "Mechanically, TFAP2A and TFAP2C are capable of binding the ERBB2 promoter, and in collaboration with other transcription factors, such as Ku protein and Yin Yang 1, they significantly promote ERBB2 expression in breast cancer cells." (PMID 37291585, 2023). "The SK-BR-3 cell line has amplified ERBb2 and high levels of EGFR, representing well-accepted model systems of ERBb2-positive breast cancer." (PMID 38090376, 2023). "Given that pCR rate for women with HR-/ERBB2+ disease was also highest of all breast cancer subtypes, as shown in this and other studies, disparate response to similar treatment plans suggested the existence of underexplored biological differences." (PMID 36995716, 2023). "Transcriptomic analysis of the MIND models again identified high expression of ERBB2 and Ki67 as risk factors, as well as additional factors such as S100A8/A9 and FOXD1, which are described to drive breast cancer proliferation." (PMID 37116492, 2023). "HER2 protein overexpression and/or ERBB2 gene amplification occurs in up to 20% of breast cancers (BCs), known as HER2-positive BCs." (PMID 40028485, 2023). "For instance, amplification of the HER2 (ERBB2) gene on chromosome 17 and the overexpression of HER2 protein play a crucial role in the pathogenesis of HER2-positive breast cancer." (PMID 37760522, 2023). "The antiproliferative effects of ERBB2-specific antisense oligonucleotides have been described in HER-2 overexpressing breast cancer cells in a range of concentrations of 1–20 μM." (PMID 37108234, 2023). "The ability of THC to treat ErbB2-positive breast cancer, has been evaluated in some recent studies." (PMID 37521486, 2023). "The Her2/neu transgenic mouse model was used in this study because the overexpression of the Erbb2 gene drives the development of ER-negative mammary tumors, and this mouse model is suitable for studying human breast cancer." (PMID 37240357, 2023). "Lapatinib and neratinib are ErbB2-targeting drugs that have been approved to treat HER2-positive breast cancer." (PMID 36768973, 2023). "The 5-years disease free survival rate calculated for ERBB2+ triple negative, Luminal-A, and Luminal-B molecular type breast cancer from the patient population were 85%, 76%, 81%, and 75%, respectively." (PMID 38114526, 2023).
breast cancer (continued). "Shc3 is also required for the drug resistance breast cancer cells by mediating nuclear translocation of ErbB2, thereby facilitating P‐gp expression by promoting ErbB2‐COX2‐MDR1 axis activity." (PMID 36880347, 2023). "It is interesting to note that human chromosome 8q contains the MYC locus and chromosome 17q contains the ERBB2 locus, with amplification of these two loci highly correlated in human breast cancer." (PMID 37805590, 2023). "In breast cancer, biCAR-T cells targeting ErbB2 and MUC1 in vitro, showed efficient antitumor activity." (PMID 36717905, 2023). "The initial classification categorizing breast cancers into five groups, luminal A, luminal B, ERBB2-overexpressing, basal-like and normal-like, was later supplemented by an additional group, claudin-low tumors." (PMID 37345027, 2023). "Activated PPARγ enables ERBB2-positive breast cancer cells that produce high levels of fat to convert fatty acids into triglycerides, allowing these cells to avoid cell death caused by lipotoxicity." (PMID 37251321, 2023). "In the case of TATs for breast cancer, we observed that ERBB2 was exclusively expressed in the so‐called HER2‐positive breast cancer, due to the presence of an amplified gene." (PMID 37740463, 2023). "Several ERBB2/HER-2 targeting therapeutics have been approved for the treatment of solid tumors, such as breast cancer and lung cancer." (PMID 37373090, 2023). "For example, in a mouse model of ErbB2-driven metastatic breast cancer, THC treatment was able to reduce tumor growth, as well as the amount and severity of lung metastases." (PMID 37521486, 2023). "A microfluidic LSPR sensor device was used to identify four breast cancer protein markers (ErbB2, CA 125, CEA, and CA 15-3) in human blood." (PMID 36979608, 2023). "TFAP2C increases ERBB-related genes (EGFR, ERBB2, ERBB3), which mediate oncogenesis in ERBB2/HER2-amplified breast cancer." (PMID 37291585, 2023). "Human epidermal growth factor receptor 2–positive (HER2+) breast cancer — referring to breast cancer tumors that have HER2, also known as ERBB2, overexpression and/or amplification — accounts for 20%–30% of all breast cancer cases." (PMID 37463446, 2023). "An overwhelming majority of the mutations were predicted as PGs, which interestingly included Her2 (also known as Erbb2), a well-known OG in breast cancer." (PMID 37958330, 2023). "Further research has shown that activated ErbB2 stimulates GLS expression in breast cancer cells through the PI3K/Akt-independent NF-κB pathway." (PMID 36959802, 2023). "This is epitomized by the application of ErbB2‐targeted drugs in a subset of breast cancers, of BRAF inhibitors in melanomas, of drugs targeting liabilities due to mutated BRCA in gynecological tumors, to cite some key examples." (PMID 36722641, 2023). "We further found that Shc3 acts as a link mediating the binding between EphA2 and ErbB2 in breast cancer cells, resulting in increased activation of MAP kinase and AKT signaling pathways." (PMID 36880347, 2023). "Studies have demonstrated that combining lapatinib, a tyrosine kinase inhibitor, with anti-ErbB2 antibodies enhanced apoptosis in breast cancer cells that overexpress ErbB2." (PMID 37754530, 2023). "More than half of breast cancers historically categorized as HER2-negative express low levels of HER2 (ERBB2), defined as immunohistochemically (IHC) 1+ or 2+ and lack of HER2 gene amplification measured by in situ hybridization." (PMID 37148499, 2023). "Breast cancers with an increased vascular index on Microvascular US about 8 times more frequently showed the SNP rs1136201 in ERBB2 compared with those with a lower vascular index." (PMID 37120792, 2023). "The gene enrichment analysis, functional enrichment, and pathway analysis showed that EGFR and IGF1R are genes at the initial phase of the TNBC-specific pathway, and ERBB2 and 1ESR are involved in the hormone-dependent breast cancer pathway." (PMID 37629702, 2023).
breast cancer (continued). "HER2 protein is encoded by the ERBB2 gene and is a molecular target for HER2-overexpressing breast cancer." (PMID 37759508, 2023). "The antibody‐drug conjugate trastuzumab emtansine (T‐DM1) is approved for human epidermal growth factor receptor 2 (HER2/ERBB2)–positive breast cancer." (PMID 37119523, 2023). "A growing body of evidence indicates that ErbB2, as well as other ErbB family members and their ligands, exist and function in breast cancer." (PMID 36880347, 2023). "Targeted therapies directed against ERBB2 are the cornerstone of medical treatment for ERBB2-positive breast cancers but are contraindicated during pregnancy." (PMID 37883083, 2023). "Breast cancers can be subdivided into several subtypes according to hormone receptors (HRs, including the estrogen receptor and the progesterone receptor) and human epidermal growth factor receptor 2 (HER2, or ERBB2) status." (PMID 37607916, 2023). "in Taiwanese patients with breast cancer identified PIK3CA as one of the most frequently mutated genes in 38% of the study population, followed by ERBB2 (23%), ESR1 (10%), AKT1 (6%), and BRCA2 (5%) mutations." (PMID 37655108, 2023). "Despite Tz effectiveness, about 35% of ERBB2+ breast cancer patients are de novo resistant to Tz, and among those that are responsive, about 70% will eventually become resistant within one year of treatment." (PMID 37367744, 2023). "Human epidermal growth factor receptor 2 (ErbB2/HER2) is a tyrosine kinase receptor that is overexpressed in 25% of primary human breast cancers, as well as in multiple other cancers." (PMID 36912768, 2023). "Accurate identification of three breast cancer cell biomarkers including EpCAM, ErbB2, and CD44 was achieved by using PEGylated Ag–Au hollow nanospheres based on Raman imaging." (PMID 37323623, 2023). "Most recurrent events in ERBB2-positive breast cancer have been reported to occur within 3 years, and this duration appears sufficient to provide adequate evidence to support efficacy and safety conclusions." (PMID 36721174, 2023). "ERBB2, a characteristic oncogene, is one of the highest-response therapeutic targets in breast cancer." (PMID 37991016, 2023). "Some miRNAs were identified as upstream regulators that were upregulated in the ERBB2-high group compared with the ERBB2-low group and have been reported as cell proliferation markers for breast cancer." (PMID 37759508, 2023). "HER2+ breast cancer is characterized by overexpression of human epidermal growth factor receptor 2 (HER2, HER2/neu, erbB-2)." (PMID 37200287, 2023). "More large retrospective studies are warranted to rigorously investigate the role of endocrine resistance markers (ERBB2, BCL2, and CCND1) in screening FA patients with a high recurrence risk and increased risk of breast cancer." (PMID 37328469, 2023). "And ex vivo biodistribution and PET imaging of F-18 labeled ErbB2 aptamers containing 3’-idT cap were evaluated and compared with unmodified aptamer in mice with ErbB2-expressing breast cancer xenografts." (PMID 37729138, 2023). "From breast cancer actionability, PIK3CA (ESCAT Tier IA) was reported in 39.4% (n = 97), AKT1 mutation (ESCAT Tier IIB) in 45.9% (n = 113), and ERBB2 mutation (ESCAT Tier IIB) in 17.1% (n = 42) of early-stage Taiwanese breast cancers." (PMID 37760445, 2023). "This is in line with past papers, which have also concluded that ERBB2 amplification detection via NGS in GC is less reliable than in breast cancer." (PMID 37072406, 2023). "One patient with HER2 positive breast cancer in longer oligo-R group was performed FoundationOne CDx using the specimen taken from metastasis site, and no ERBB2 mutation was found." (PMID 37715134, 2023). "The acetylation of the conserved lysine motif (K154/155) of PPARγ1 promotes lipid synthesis in ErbB2-positive breast cancer cells." (PMID 36647790, 2023).